IL15 (interleukin 15)
Diseases named in the same sentence as IL15 in open-access papers (continued):
Sharing a sentence is not in itself a finding about the gene and the disease.
tumor (continued). "According to the study, NK cells at rest are not hazardous to tumour cells, however NK cells that have been activated by IL‐2 or IL‐15 have the ability to prevent tumour growth." (PMID 37337404, 2023). "Interestingly, intravenous administration of IL‐15 induced a significant increase of circulating CD8+ T and NK cells in patients with different tumours." (PMID 37592827, 2023). "Secretion of cytokines such as IL-12, IL-15, IL-18, and IL-21 by so-called TRUCKs can help to promote the cells’ proliferative activity and reshape the TME, in addition to the attraction of bystanding anti-tumor immune cells." (PMID 37443804, 2023). "We showed previously that the mouse cross-reactive KD033-surrogate had increased safety compared to the non-targeting IL-15 and significant anti-tumor activity in mouse tumor models that are non- or minimally responsive to IL-15 or anti-PD-L1 monotherapy." (PMID 36454338, 2023). "GPC3 CAR-T cells expressing IL-15 and IL-21 exhibited significantly greater anti-tumor efficacy in mice compared to CAR-T cells without IL-21 expression." (PMID 38090585, 2023). "Encouragingly, GvHD effects were not different between NSG-Tg (Hu-IL15) or standard NSG mice receiving resting or exercise-mobilized lymphocytes in the absence of tumor." (PMID 37077913, 2023). "Systemic administration of biNV-IL-15 achieves targeted delivery of IL-15 to tumor-specific T cells, diminishes non-specific systemic immune stimulation, and maximizes CTL activation to drive tumor killing and immunological memory." (PMID 37875481, 2023). "Moreover, myeloid cells promote tumor growth by secretion of pro-inflammatory cytokines such as IL1b, IL6 and IL15, which have been shown to promote inflammation and tumor growth." (PMID 36761972, 2023). "Combination of ADU-S100 and cyto-IL-15 can lead to complete regression of TRAMP-C2 tumors treated at 100 mm3 volume leaving none or minimal tumor tissue sample for analysis." (PMID 37465665, 2023). "IL-15 (interleukin) promotes a pro-inflammatory phenotype of microglia and the cytotoxic activity of natural killer (NK) cells in TME, which also promote the production of IFN-γ, and counteracted tumor growth." (PMID 37598273, 2023). "Next we evaluated whether dual expression of IL-15 and K2-Fc impacted the kinetics of immune cell expansion and CD134, CD137, PD-1 and CD16 expression during tumor cell killing." (PMID 37923822, 2023). "In addition to the administration of IL-15, exercise-induced increases in IL-15 were reported to enhance CD8+ T cell immunity and suppress tumor growth in mouse models." (PMID 38067295, 2023). "Our data demonstrate that following adoptive transfer, TCR-engineered TSCM-like cells generated in culture with IL-7/IL-15 maintain a reservoir in the tdLNs accounting for nearly a quarter of all CD90.1+ cells, whereas tumor-infiltrating cells express a differentiated effector memory phenotype." (PMID 37400675, 2023). "Resting NK cells are defined as naïve NK cells not activated by cytokines (IL-2 or IL-15) or tumor priming, thus lacking markers of a recent stimulation (e.g. CD69, CD25)." (PMID 38071322, 2023). "In addition, IL-15 has been reported to protect antigen-activated NKT cells from macrophage-mediated functional suppression, thereby enabling significant tumor control." (PMID 37371081, 2023). "Prolonged IL-15 treatment to isolated human intestinal intraepithelial lymphocytes leads to massive production of IFN-γ and IL-10, eventually resulted in enhanced cytotoxicity against tumor cells." (PMID 38106519, 2023). "Since combination of checkpoint inhibitors with cyto-IL-15 did not lead to additional anti-tumor activity, we sought to investigate new combinations to improve the efficacy of cyto-IL-15." (PMID 37465665, 2023).
tumor (continued). "Alongside the secretion of interferon cytokines, detectable traces of the TNF-α are also found from IL-15 activated ILC1 cells, supporting the hypothesis that ILC1 cells suppress early-stage tumours via apoptotic lysis of tumour cells." (PMID 35557940, 2022). "Similarly, the administration of the IL-15/IL-15Rα immune complex induces activation and expansion of both NK and CD8 T cells, which become highly functional with enhanced anti-tumor responses." (PMID 36231109, 2022). "IL-15 is also a key factor in the development, proliferation, and activation of NK cells and CD8+ T cells, which are able to destroy cancer cells in the tumor microenvironment." (PMID 36467072, 2022). "Overexpressing IL-15 or IL-15 receptor complex has been evaluated in CD19-CAR, CD123-CAR, and NKG2D-CAR NK cells, with significantly improved NK cell survival rate and enhanced anti-tumor efficacy." (PMID 35806311, 2022). "While IFN-γ is required for successful tumor destruction, supra-physiological IFN-γ levels may accumulate particularly in case of co-expressed IL18 that can cooperate with IL12 or IL15 to further increase IFN-γ production." (PMID 36700225, 2022). "First, IL-15 is expressed to support NK cell proliferation, persistence, and homing in a xenograft NSG mouse model, while retaining the specific cytotoxicity of traditional anti-CD19 CAR constructs against CD19+ tumor targets." (PMID 36428748, 2022). "The CD16/IL-15/CD33 TriKE not only was able to enhance NK function against CD33+ cell lines and AML blasts, but also to expand and sustain human NK cells in vivo, reducing tumor burden in a xenograft model." (PMID 35493522, 2022). "To rule out the possibility the observed anti‐tumour effects were cytokine‐specific, we performed immunotherapy with IL15 in wild‐type mice bearing syngeneic solid tumour models." (PMID 35758207, 2022). "IL15Rα-IL15-armed OVs, in conjunction with ACT, rapamycin, and celecoxib provide potent antitumor effects against brain tumors, suggesting that complex but rationally designed therapeutic combinations can produce robust anti-tumor effects." (PMID 36221123, 2022). "In the same way as IL-15 incorporation, the use of transgenes coding for chemokine receptors could promote CAR-NK trafficking in tumor sites." (PMID 35954502, 2022). "IL-15 is a potent stimulator of CD8+ T cells and NK cells via the activation of IL-15Rα, IL-2Rβ (also named CD122), and IL-2Rγ (also named CD132), which share receptors with IL-2, IL-4, IL-7, IL-9, and IL-21, and thereby reduces tumor burden." (PMID 36439125, 2022). "The expression levels of BDNF, IL15, and MSTN were significantly higher in tumor tissues than in paraneoplastic tissues, while the expression level of FNDC5 was significantly reduced in tumor tissues." (PMID 36733390, 2022). "IL15 has been a primary cytokine of interest in immunotherapy due to its ability to activate the main anti‐tumour cell effectors, but does not, in contrast to IL2, stimulate immune‐suppressing regulatory T cells (Treg)." (PMID 35758207, 2022). "In addition, a higher killing was accompanied by an IL-15-mediated overexpression of cytotoxic markers and molecules like CD56, NKG2A, IFN-γ, TNF-α, and higher direct killing against several adherent tumor cell lines." (PMID 36429001, 2022). "A potential role of IL-15 in shaping human g1 ILC phenotype and their anti-tumor functions is advocated by the increased expression of IL-15 in chRCC compared to ccRCC, and the positive correlation between IL-15 levels and ILC1 signature enrichment within the chRCC patient cohort." (PMID 36372017, 2022). "Without accessory transgenes (CCL5 and IL-15), high doses of unarmed oncolytic-adenovirus controlled tumour growth without the need for CAR T cells, but synergised with CAR T cells at lower doses, with modest effects on CAR T cell persistence noted." (PMID 35205725, 2022).
tumor (continued). "Several factors could affect apparent number of CD4+ T cells in tumor: recruitment (CXCL9/10), proliferation (IL‐15), and death (IL‐2)." (PMID 34898004, 2022). "However, NK cell activity can be altered by numerous components of the tumor microenvironment, including immunosuppressive cytokines, such as TGF-β, and pro-inflammatory cytokines, such as IL-12, IL-15, IL-18, and IL-21." (PMID 35203609, 2022). "These traits have made manipulation of IL-15 expression an appealing strategy to enhance the anti-tumor activity of a variety NK cells populations without the need to supplement the cell production cultures with high doses of cytokines." (PMID 35185932, 2022). "IL-1, IL-6, IL-11, IL-15, IL-17, IL-23, and TNF-α are representative proinflammatory cytokines promoting tumor cell differentiation, proliferation, and survival that build up the tumor microenvironment and tumor inflammation." (PMID 36438839, 2022). "IL-15 secreting CAR-transduced cells showed enhanced proliferation and anti-tumor activity in a HepG2 xenograft mouse model compared to CAR-transduced cells without IL-15." (PMID 35806311, 2022). "Since hypoxia together with IL-15 can induce glycolysis in NK cells, this might be another important aspect explaining how IL-15 in the TME promotes anti-tumor responses of g1 ILCs." (PMID 36372017, 2022). "As IL-15 plays a critical role in the activation of both CD8+ T cells and NK cells, this result is consistent with a functional contribution of both the adaptive immune system and NK cells in ONP-302-induced modulation of tumor growth." (PMID 36059473, 2022). "Interestingly, the treatment of B16F10 in tumor-bearing mice with a bifunctional TGF-β trap/IL-15 protein complex, HCW9218 also enhanced NK and CD8 T cell-mediated anti-tumor responses." (PMID 36231109, 2022). "Pre-activated NK cells ex vivo by several cytokines, primarily including IL-12, IL-15, and IL-18, could be endowed with memory-like features, termed cytokine-induced memory-like NK cells (CIML-NK), and then last to exert an anti-tumor function." (PMID 36246629, 2022). "This can further be improved by the knockout of the IL-15 signaling regulatory protein CISH, creating iPS-NK cells with improved metabolic profile, increased expansion and persistence, and enhanced cytotoxicity in human AML xenograft tumor models." (PMID 35565395, 2022). "Finally, the expression of IL-15 and HGF genes, known to promote tumor cell survival, was higher at diagnosis than in paired relapse samples." (PMID 36230815, 2022). "Tumor growth kinetics were compared to HSC‐engrafted NSG‐Tg(Hu‐IL15) and NSG mice that were not treated with the anti‐NKp46 antibody." (PMID 35959876, 2022). "In contrast, CAR/IL-15 NK cells in the other model using the MOLM-13 cell line in the same study saw powerful anti-tumor activity without severe toxicity." (PMID 35806311, 2022). "In addition to tumor-infiltrating CAR T cells, other immune cells, such as NK cells, NKT cells, endogenous T cells, and innate lymphoid cells, are responsive to IL-15." (PMID 34177932, 2021). "IL-18 neutralization, but not IL-12 or IL-15 neutralization, interfered with PD-L1 up-regulation on NK cells, suggesting that IL-18 produced during tumor-stimulation of PBMC contributes to enhance PD-L1 expression on NK cells." (PMID 34616407, 2021). "IgG2 presents IL-15 to CD8+ T cell through APC and its effect is reflected in robust Ag-specific memory T cell response, which is required for vaccine development and anti-tumor therapy." (PMID 33953717, 2021). "The CD44v6-CAR-T cell that aimed to secrete IL-7 and IL-15 cytokines illustrated the greater anti-tumor function against MM cells with no toxic effects on normal keratinocytes and hematopoietic stem cells." (PMID 33781320, 2021). "At the lower dose of 0.3 × 105 cells/mouse which secreted IL-15:IL-15Rα in the range of 10–25 pg/mL, the immunization did not inhibit tumor growth effectively." (PMID 34439192, 2021).
tumor (continued). "Moreover, GD2 CAR T cells expressing IL-15 were enriched in stem-cell-like cells and promoted enhanced CAR T antitumour effect and expansion in a paediatric tumour model of neuroblastoma." (PMID 34831165, 2021). "Additionally, IL-15 in a HCC animal model promotes tumor control, based on the long-term expansion of tumor-specific CD8 T cells, increasing IFNγ secretion and cytotoxicity, and also decreasing the expression of co-inhibitory molecules on dendritic cells." (PMID 33923463, 2021). "In order to minimize systemic toxicity and induce the accumulation of high cytokine concentrations at the tumour site, CAR‐T cells were modified to produce IL‐12, IL‐18, IL‐7, IL‐15 and IL‐21 cytokines, and activation and persistence of CAR‐T cells were, therefore, enhanced in vivo." (PMID 34585512, 2021). "We showed that the MMC-treated IL-15:IL-15Rα-B16F10-OVA vaccine inhibited the tumor growth of B16F10-OVA by enhancing splenic central memory CD8+ T cells, tumor-infiltrating NK cells, and tumor-infiltrating effector memory CD4+ and CD8+ T cells." (PMID 34439192, 2021). "Combining blockade of the inhibitory receptor CD96 or administration of low-dose IL-15 with CIS inhibition could further boost NK cell activity and enhance protection against tumor metastasis." (PMID 33946954, 2021). "This could inform therapeutic strategies for combining adoptive NK cell transfer and IL-15 administration with targeting of STAT3 in cancer and attenuating the known interference of STAT3 inhibition with NK cell anti-tumor activity." (PMID 33782423, 2021). "Various cytokines, such as IL-13, IL-15, and IL-32, and surface proteins, including CD47, CD40, and CD28, provide the direct molecular bridge between tumor cells and adjacent cells, resulting in tumor progression." (PMID 34830466, 2021). "Although for genes like Il15 we did not observe any difference between healthy and tumor-bearing mice in Ficoll or Parsortix samples; others, such as Egr1, Zc3h12a, Klf4, or Nfat5, allowed distinguishing for cancer or CTC presence." (PMID 35153760, 2021). "As for M1 macrophages, it could suppress tumor growth by both cytophagocytic effects and the production of TNF-α, reactive oxygen species (ROS), and cytokines like IL-1, IL-12, IL-15, and IL-18 to enhance Th1 response." (PMID 34650926, 2021). "In both tumor types pFUS increased IL1α, IL1ß, IL2, IL6, IL12p40, IL15, IL17, TNFα, and VCAM." (PMID 33801627, 2021). "IL-15-secreting CAR T cells had enhanced effector functions, increased levels of the anti-apoptotic protein Bcl-2, reduced expression of PD-1, and demonstrated greater tumour control and persistence in vivo." (PMID 34885108, 2021). "Moreover, in an explorative response prediction model, the combination of protein markers (CXCL9, CXCL10, IL-15, CASP8, and ADA) resulted in higher accuracy in predicting response than tumor PD-L1 expression or each protein assayed individually." (PMID 34206510, 2021). "The addition of IL-12, but not IL-7 or IL-15, to the cells improved tumor growth inhibition and extended survival compared with mRBC-OVA-4-1BBL and the PBS control, resulting in 4/8 cures." (PMID 33976146, 2021). "However, cells in the ALCL tumor microenvironment can be assumed to produce IL-234,35, and in the majority of cases, ALCL cells produce IL-15, both accounting for IL-2R stimulation in primary ALCL." (PMID 34552066, 2021). "The humanized NSG.Tg(Hu-IL-15) with LV/hu-IL-12 transduced cells had a significant reduction in tumor volume vs non-transduced cells (p = 0.0006)." (PMID 33859303, 2021). "Moreover, IL-15 can expand and activate NK, NKTs, and memory CD8+ T cells in TME, leading to tumor destruction." (PMID 33668573, 2021). "Thus, although the focus of this work was on studying anti-tumour CAR-T cell responses, simultaneous activation of NK cells is also likely given that both CCL5 and IL-15 are key drivers of NK cell recruitment and activation." (PMID 34888493, 2021).
tumor (continued). "Immunization with IL-15:IL-15Rα-B16F10-OVA significantly delayed B16F10 tumor growth compared to the mice immunized with no virus-infected B16F10-OVA and control-B16F10-OVA." (PMID 34439192, 2021). "Hence, additional strategies aimed at manipulating tumor microenvironment (TME) are required, for example, armoring CAR NK or CAR-CIML NK cells to express cytokines (like IL-12 and IL-15) and incorporation of TGFβ traps." (PMID 34863287, 2021). "Although IL-7/IL-15-treated polyclonal T cells have less differentiation and more anti-tumor efficiency, they either show no significant T cell expansion advantage or a small T cell and CAR T cell expansion compared to IL-2 only-treated cells." (PMID 34217218, 2021). "It is known that cytokines like IL-12, IL-15 and IL-18 downregulate the TGF-β receptor and its signaling pathway which may contribute to the enhanced anti-tumor responses by the CIML NK cells." (PMID 34863287, 2021). "Due to the stimulatory effects on NK cells, IL-15 agents have been used in combination with anti-cancer monoclonal antibodies, resulting in increased antibody-dependent cell cytotoxicity (ADCC) and anti-tumor efficacy." (PMID 33671252, 2021). "Similarly, genetic deletion of a negative regulator of IL-15 signaling, called cytokine-inducible SH2-containing protein or CIS, in iPSC-NK cells led to improved anti-tumor function, both in vitro and in vivo in a leukemia xenograft model." (PMID 33120910, 2020). "Further combination therapy of cancer-targeting NIR-PIT with both IL-15 and an immune-checkpoint blockade or Treg-targeting NIR-PIT could theoretically enhance tumor immunity." (PMID 32927646, 2020). "Many strategies such as expressing chemokine receptors CXCR2/CCR2b, CXCR3 and use of oncolytic virus to secrete chemokines RANTES, IL-15 to drive CART cells to tumor sites are being actively tested to drive CART cells to tumor sites in non-GBM tumors." (PMID 33281826, 2020). "Such non-T cytotoxic cells including NK cells were more prominent in day 4 than day 7, suggesting that IL-15 stimulates the cytotoxic activity of T and non-T cell population at acute and subacute phase of tumor rejection." (PMID 32927646, 2020). "Importantly, 25% (2/8) of animals obtained complete tumor regression and remained tumor free following GET with plasmid IL-15/IL-15Rα." (PMID 33628206, 2020). "In this model there was an abscopal effect obtained with reduction in the size of the tumor not injected with anti-CD40 beyond that mediated by IL-15 alone." (PMID 32508818, 2020). "IL-15 is dynamically regulated in the TME and enhances anti-tumor immunity." (PMID 31936322, 2020). "For instance, the ABE-induced upregulation of IL-15 is particularly interesting since this protein enhances the anti-tumor activity of natural killer (NK) cells by potentiating NKG2D receptors and is a possible candidate molecule for anti-tumor therapy." (PMID 32183239, 2020). "By contrast, a recent report showed that chronic stimulation of adaptive NK cells from HCMV seropositive donors via NKG2C and IL-15, NKp30, or NKG2D increased PD-1 and LAG-3 surface expression, downregulating NK activity during subsequent interactions with tumor targets." (PMID 32153582, 2020). "NKG2D-CAR T cells but not Empty control T cells proliferated in response to NKG2D-ligand-bearing tumor targets, but not B16 controls with IL-15 stimulated T cells serving as positive controls." (PMID 33384686, 2020). "CD19 CAR T-cells engineered to constitutively secrete IL-15 demonstrated improved proliferation upon exposure to its cognate antigen, improved CAR T-cell persistence, reduced expression of the PD-1 exhaustion marker, and improved tumor clearance in vivo." (PMID 33643299, 2020). "The amount of IL-15 expressed and the presence or absence of IL-15Rα in the treated tumors did not significantly affect the tumor regression and long-term survival." (PMID 33096755, 2020).